TRPV4 (transient receptor potential cation channel subfamily V member 4)
Diseases named in the same sentence as TRPV4 in open-access papers (continued):
Sharing a sentence is not in itself a finding about the gene and the disease.
Obesity (29 papers, 2011 to 2026). Accumulation of substantial excess body fat. "TRPV4−/− mice were reported to display impaired osmotic and pain sensation, reduced endothelium-dependent vasodilation, and increased susceptibility to obesity." (PMID 41024271, 2025). "In our previous study, we demonstrated that hypothalamic TRPV4 overexpression increased obesity susceptibility." (PMID 40076916, 2025). "TRPV4 is closely associated with obesity and asthma, and to target TRPV4 for the treatment of obese asthma, the key is to find effective activators." (PMID 38365763, 2024). "Obesity has been linked to reduced TRPV4-dependent dilation in mesenteric arteries resulting from peroxynitrite-dependent inactivation of AKAP150." (PMID 37507971, 2023). "Mice with a null mutation for TRPV4, or wild-type mice treated with a TRPV4 antagonist, showed elevated thermogenesis in adipose tissues and were protected from diet-induced obesity, adipose inflammation, and insulin resistance." (PMID 36232935, 2022). "It is thus apparent that the pathophysiological relevance of TRPV4 to endothelial dysfunction associated with obesity is yet to be determined and warrants further investigation." (PMID 34616307, 2021). "A previous study of mice with a global TRPV4 knockout showed that reduced TRPV4 expression increased age‐related and obesity‐induced OA susceptibility." (PMID 32237113, 2020). "In studies involving rats, diminished TRPV4 expression and function have been associated with endothelial dysfunction in mesenteric arteries under conditions of genetic and salt‐induced hypertension, obesity, and aging." (PMID 39744893, 2025). "Moreover, TRPV4-deficient mice have an increased risk of obesity-related OA." (PMID 33919210, 2021). "Conversely, TRPV4 deficiency enhances WAT browning, increases energy expenditure and protects against diet-induced obesity and insulin resistance." (PMID 41596403, 2026). "Conversely, adipose tissue-specific TRPV4 knockout mice exhibited obesity resistance by promoting the browning of white adipocytes." (PMID 40076916, 2025). "Examine the expression and function of TRPV4 in human obesity and developing TRPV4 specific antagonist and in vivo examination of the new compounds is warranted." (PMID 34249940, 2021). "It has also been reported that treadmill running and rutin ameliorate HFD-induced obesity in mice by suppressing the expression of TRPV4 in adipocytes." (PMID 34249940, 2021). "The contradictory role of TRPV4 in adipogenesis and obesity requires further research, especially regarding the effects of lifestyle intervention on its expression." (PMID 32545529, 2020). "We have previously reported that Trpv1 and Trpv3 mRNAs were significantly decreased, whereas Trpv2 and Trpv4 mRNAs were significantly increased in the white adipose tissue (WAT) of either db/db or diet-induced obesity (DIO) mice." (PMID 33195411, 2020). "Thus, TRPV4 functions as a negative regulator of thermogenesis and represents a potential therapeutic target for obesity and metabolic disorders." (PMID 41596403, 2026). "Proteins such as TRPV4 and CaMKV emerge as promising targets for future obesity treatment." (PMID 40076916, 2025). "Collectively, these findings suggest that dysregulated TRPV4 expression could be a promising therapeutic target for the prevention and treatment of obesity." (PMID 40076916, 2025). "Moreover, the adipose tissue expresses high levels of TRPV4, and the relationship between obesity and TRPV4 has been proven in mice." (PMID 36232935, 2022). "Considering that TRPV4 expression increased in the stomach of patients with obesity, we predict that this mechanism may affect body weight." (PMID 36397882, 2022). "Furthermore, we showed for the first time that TRPV4 is widely expressed in the stomach of patients with obesity." (PMID 36397882, 2022). "Understanding the correlation between the TRPV4 expression level and BMI may provide promising targets for new strategies to combat obesity." (PMID 36397882, 2022).
Obesity (continued). "However, adipose-derived exosomes can reduce the pulmonary barrier hyperpermeability by inhibiting the TRPV4/Ca2+ pathway in HFD-induced obesity." (PMID 33716794, 2021). "However, knockout of TRPV4 has been proved to increase weight gain and promotes obesity during HFD-treatment in mice." (PMID 32175809, 2020). "Therefore, further investigation is necessary to understand the role of TRPV4 in regulating Ca2+ influx, adipogenesis and obesity." (PMID 32175809, 2020). "TRPV4 agonists promote vasorelaxation and improve cardiovascular function in a rodent type 2 diabetes model, and TRPV4 antagonists reduce high-fat diet-induced obesity, insulin resistance, and diabetes-related complications, suggesting its potential as a therapeutic target for such diseases." (PMID 33981725, 2021). "Similarly, previous studies have shown that TRPV4 KO mice (another Ca2+ entry channel) are also protected from obesity and metabolic dysfunction with exposure to HF diet suggesting that Ca2+ channels negatively regulate obesity." (PMID 29074621, 2017). "While adipocytes with TRPV4 knockdown exhibit increased respiration rate, TRPV4 knockout mice have increased energy expenditure, reduced inflammation in adipose tissue and are protected from diet-induced obesity, attesting to the positive metabolic effects of browning." (PMID 23895241, 2013). "It has been reported that the dysfunction of the TRP ion channel (TRPV4, TRPV1, TRPM4, and TRPM) is considered to be related to obesity or diabetes, and these disorders are related to appetite, insulin secretion, and autoimmune response." (PMID 34512754, 2021). "Notably, TRPV4 knockout mice exhibited elevated thermogenic gene expression in adipose tissue, attenuated HFD-induced obesity, and decreased levels of inflammatory cytokines such as TNF-α and IL-6." (PMID 40076916, 2025). "TRPV4 expression was significantly higher in patients with obesity than in those without at all sites, except the fornix." (PMID 36397882, 2022). "TRPV4 expression was compared between patients with (body mass index (BMI) ≥ 30) and without (BMI <30) obesity." (PMID 36397882, 2022). "In addition, we also found that TRP ion channel family genes (TRPV4, TRPV1, TRPM4, and TRPM5) related to obesity or diabetes were highly expressed in HBV-related HCC." (PMID 34512754, 2021). "Besides, pharmacological inhibition or deletion of TRPV4 also activates energy expenditure and protects mice from HFD-induced obesity in vivo." (PMID 32175809, 2020). "In contrast, compared with the expression in patients without obesity, TRPV4 expression was higher in patients with obesity in the greater curvature of the gastric body, the greater curvature of the antrum, the anterior wall of the gastric body, and the posterior wall of the gastric body." (PMID 36397882, 2022). "Collectively, these data indicated that HFD-induced obesity plays a protective role in VILI by alleviating the pulmonary endothelial barrier injury and inflammatory response via adipose-derived exosomes, at least partially, through inhibiting the TRPV4/Ca2+ pathway." (PMID 32073873, 2020). "In the 12q24 area there are other genes that might be involved in the phenotype including THRAP2, TBX5 and PTPN11 for cardiac and great vessel anomalies; TBX5, CMKLR1, and TRPV4 for skeletal defects; PRKAB1, GPR109A, and GPR109B for increased hunger and obesity." (PMID 21457577, 2011). "In addition, mice lacking TRPV4 are resistant to HFD-induced obesity." (PMID 38390373, 2023).
osteoarthritis (29 papers, 2016 to 2026). A noninflammatory degenerative joint disease occurring chiefly in older persons, characterized by degeneration of the articular cartilage, hypertrophy of bone at the margins and changes in the synovial membrane. "As such, TRPV4−/− mice exhibit a severe sex-dependent osteoarthritis (male mice are more susceptible) while the isolated chondrocytes fail to increase Ca2+ influx in response to hypo-osmotic challenge." (PMID 33395574, 2021). "TRPV4 is abundantly expressed in articular chondrocytes, and loss of TRPV4 activity leads to osteoarthritis and joint arthropathy." (PMID 34108580, 2021). "In fact, TRPV4 is highly expressed in articular chondrocytes, and loss of TRPV4 function is reportedly associated with joint arthropathy and osteoarthritis." (PMID 33648469, 2021). "Conversely, loss of TRPV4 in chondrocytes in adulthood protects mice from aging-associated osteoarthritis." (PMID 33537292, 2020). "Growing evidence suggests that TRPV4 plays an important role in mediating cellular and tissue inflammation, and studies of chondrocyte-specific TRPV4 knockout mice reported a decreased severity of age-associated osteoarthritis." (PMID 35207158, 2022). "During osteoarthritis (OA) progression, hypotonic stimuli enhance TRPV4-mediated Ca2+ influx and induce RANKL mRNA expression, whereas knockdown of TRPV4 reduces osteoclast numbers and inhibits bone loss." (PMID 40698068, 2025). "In line with previous studies, TRPV4 plays a critical role in the development of chondrogenesis and osteoarthritis." (PMID 40013941, 2025). "The findings also suggest potential therapeutic implications for targeting TRPV4 in conditions such as osteoarthritis, and for enhancing matrix formation in tissue-engineered cartilage." (PMID 38540712, 2024). "To date, several synthetic molecules that modulate TRPV4 channels have been developed to aim at treating diseases such as osteoarthritis, respiratory diseases, cancers, gastrointestinal disorders and pain." (PMID 37371124, 2023). "Piezo1 and TRPV4 have been shown to work synergistically in several pathological states, such as osteoarthritis and pancreatitis." (PMID 34795674, 2021). "Adipose-derived stem cells from TRPV4 knockdown mice tend to undergo adipogenic and osteogenic differentiation and resist chondrogenic differentiation, and TRPV4 knockdown mice develop severe osteoarthritis." (PMID 33775217, 2021). "Previous studies have suggested distinct roles for TRPV4 mechanotransduction in osteoarthritis (OA) subtypes." (PMID 33537292, 2020). "More specifically, primary chondrocytes represent a cellular model for joint disease with involvement of TRPV4 in cartilage maintenance as well as arthritis/osteoarthritis." (PMID 27247148, 2016). "In addition, Atobe and al. have recently reported on the new TRPV4 agonist quinazolin-4(3 H)-one, a derivative intended to treat osteoarthritis." (PMID 37371124, 2023). "TRPV4 activators may offer a promising therapeutic option for preventing the progression of osteoarthritis." (PMID 34330980, 2021). "Moreover, global deletion of TRPV4 in mice increases bone mass due to impaired osteoclast differentiation and accelerates the progression of age-dependent and obesity-induced osteoarthritis." (PMID 33537292, 2020). "Because TRPV4 also regulates the chondrogenic transcription factor SOX9, TRPV4 could indeed play a key role in osteoarthritis and the modulation of the chondrocyte phenotype." (PMID 29693628, 2018). "However, the role of TRPV4 in the progression of osteoarthritis (OA) is controversial." (PMID 34330980, 2021). "In animal models, TRPV4 antagonists such as HC-067047, RN-1734, and GSK2193874 have therapeutic effects on many disorders, including cardiovascular and ocular diseases, osteoarthritis, and bladder hyperactivity." (PMID 38730655, 2024). "However, to which extent TRPV4 protects against progression of osteoarthritis remains unclear." (PMID 31358810, 2019).
osteoarthritis (continued). "However, TRPV4 could play a key role in osteoarthritis and cartilage repair." (PMID 29693628, 2018). "The exception was represented by patient 6, in whom the expression of TRPV4 and TRPM8 channels was similar to control tissue and TRPA1, TRPV1, and TRPV2 were expressed, although at a lower level, also in the tissue used as control (probably due to an initial degree of osteoarthritis in this tissue)." (PMID 32955611, 2021). "Trpv4 gene deletion did not suppress the development of osteoarthritis pathologically in MIA rats." (PMID 34396019, 2021).
pulmonary edema (29 papers, 2017 to 2025). Accumulation of fluid in the lung tissues causing disturbance of the gas exchange that may lead to respiratory failure. "TRPV4 has recently emerged as a pharmacological target for the treatment of pulmonary oedema caused by COVID-19 (coronavirus disease of 2019)." (PMID 33081023, 2020). "Moreover, the high prevalence disorders are usually associated with disruptions of Ca2+ homeostasis and TRPV4 function, such as pulmonary edema due to pulmonary venous hypertension." (PMID 37529798, 2022). "And one study suggested that the occurrence of pulmonary edema in COVID-19 patients may be related to the radio-permeable TRPV4 channel, and the pulmonary edema caused by the virus can be alleviated by TRPV4 inhibitors." (PMID 33252122, 2020). "Mechanical activation of TRPV4 ion channels has been implicated in enhanced vascularpermeability and pulmonary edema, and overexpression of the CD98 HH domain by transfection withCD98 HH can inhibit the force transfer from β1-integrin to TRPV4 that mediates thisresponse." (PMID 31803860, 2019). "TRPV4 ion channels can beactivated within 4 ms after mechanical forces are transmitted across cell surface receptors,and mechanical activation of these channels, such as associated with breathing motions orvascular pressure, has been shown to contribute to pulmonary edema progression." (PMID 31803860, 2019). "Once in the tissue, these particles can induce the development of pulmonary edema by increasing the expression of the TRPV4 gene, responsible for coding the TRPV4 osmosis regulation ion channel." (PMID 41300983, 2025). "Trpv4 is recognised as a druggable target in pulmonary edema and congestive heart failure; however, so far, only GSK2798745, a Trpv4 antagonist, has entered clinical trials." (PMID 38799508, 2024). "Randhawa and Jaggi demonstrated that the TRPV4 channel played a crucial regulatory role in various biological processes, including the development of pulmonary edema in heart failure and blood flow–induced atherosclerosis." (PMID 39742020, 2024). "In this context, there is evidence that implicates TRPV4 and TRPC6 channels in pulmonary edema as well as TRPV4 and TRPM7 channels in pulmonary fibrosis." (PMID 35053369, 2022). "We tested the selective TRPV4 antagonist GSK2193874 (GSK219) because TRPV4 antagonists are in clinical development for the treatment of pulmonary edema during heart failure." (PMID 32471994, 2020). "This has prompted the design of clinicals trials to evaluate the effects of the GSK2798745 molecule, a specific TRPV4 inhibitor, in some conditions such as heart failure, pulmonary edema and cough." (PMID 32481620, 2020). "As a transient receptor potential cation channel subfamily V member 4 (TRPV4) antagonist, GSK2798745 was developed as a novel therapeutic intervention for the treatment of pulmonary edema associated with heart failure (HF)." (PMID 31547243, 2019). "There are chemical inhibitors of TRPV4 activity that are currently in Phase II clinicaltrials for treatment of pulmonary edema in humans, which demonstrates the clinical relevance of this target." (PMID 31803860, 2019). "TRPV4 is a calcium-permeable channel involved in barrier permeability, which blockade has been shown to prevent and resolve pulmonary edema." (PMID 29026201, 2017). "In addition, inhibition of the channel with GSK3491943 and GSK3527497 can mitigate TRPV4-induced pulmonary edema." (PMID 36549871, 2023). "Furthermore, GlaxoSmithKline have reported several clinical trials utilizing TRPV4 antagonists for the treatment of various edema indications, including pulmonary edema, chronic cough, congestive heart failure, and macular edema [, NCT02497937, NCT02119260]." (PMID 36050779, 2022). "For example, TRPV4 is essential for endothelial barrier integrity, and TRPV4 inhibitors could be beneficial for pulmonary edema." (PMID 33981725, 2021).
pulmonary edema (continued). "TRPV4 activation led to a disintegration of tight junctions and TRPV4 inhibition decreases the vascular endothelial permeability and thereby counteracts pulmonary edema induced by heart failure." (PMID 32974355, 2020). "Despite this, there is promising data to suggest blockade of TRPV4 may prove beneficial in HF patients; the pulmonary endothelial-localized TRPV4 channel has been shown to play a role in pulmonary venous pressure-induced formation of pulmonary oedema in HF." (PMID 33013458, 2020). "Moreover, pharmaceutical companies have considered TRPV4 a promising drug target to treat disease, e.g. bladder dysfunction, sepsis, and pulmonary edema, giving rise to novel selective small molecule modulators, such as the activator, GSK1016790A, and several selective inhibitors." (PMID 29293584, 2018). "The isolated perfused and ventilated lung, for example, has been instrumental in toxicant screening, in highlighting TRPV4's role in ventilator-induced alveolar permeability, as well as in the investigation of H2O2-induced pulmonary edema." (PMID 40532320, 2025). "A TRPV4 antagonist, GSK2798745, is currently being administered to patients in a phase II clinical trial for treatment of congestive heart failure-induced pulmonary edema (NTC02497937)." (PMID 32477057, 2020). "Although TRPV4 inhibitors have been employed to treat various diseases such as pulmonary edema and heart failure, there are no commercially available low-toxic and efficient drugs hitherto." (PMID 31235786, 2019).